E2F1 (E2F transcription factor 1)
Diseases named in the same sentence as E2F1 in open-access papers (continued):
Sharing a sentence is not in itself a finding about the gene and the disease.
tumor (continued). "Additionally, the rescue assays revealed that PSMD14 exerted tumor-promoting activity in HNSCC by regulating E2F1." (PMID 33456565, 2021). "Having previously established that PAX8 is necessary for RB protein stability (PAX8 can regulate E2F1 transcription and stabilize RB protein to promote tumour cell proliferation), we hypothesized that PAX8 could also regulate TAZ in protein level." (PMID 33830648, 2021). "Furthermore, apart from a single E2F1 KO PyMT tumor, PCA separates E2F1 WT and E2F1 KO tumors into distinct clusters within the Neu and PyMT models." (PMID 33947907, 2021). "Besides, the E2F1 expression level was positively correlated with poor differentiation, tumor size, and T stage." (PMID 33986804, 2021). "Moreover, the expression level of QSOX2 reflects the activity of the tumor cell cycle and more specifically the transcriptional activity of E2F1 more specifically." (PMID 34350181, 2021). "For instance, in oesophageal squamous cell carcinoma, depletion of E2F-1 may accelerated tumour cell migration in vitro by downregulating FAT1 expression." (PMID 34461908, 2021). "Here, we characterize the genome landscape of E2F WT and E2F1 KO tumors from both the Neu and PyMT models and uncover new targets that may be critical to tumor development and progression." (PMID 33947907, 2021). "Besides, the expression of E2F1 was increased by the LINC00662 overexpression in the tumor tissues of the mice." (PMID 33589572, 2021). "Interestingly, E2F1 expression was positively correlated with the expression of QSOX2 in the tumor tissue samples." (PMID 34350181, 2021). "In turn, high expression of E2F1 leads to increased cell proliferation that may result in tumor formation and progression." (PMID 33430425, 2021). "lncRNA HAGLR inhibits tumor growth of LUAD by silencing E2F1." (PMID 35095999, 2021). "Furthermore, the production of the anti-tumoral GM-CSF is controlled by the E3 promoter, which in turn is dependent on the expression of the E1a gene product, resulting in E2F-1 dependent, and therefore tumor-selective, GM-CSF expression." (PMID 34123841, 2021). "However, recent studies have also demonstrated that E2F1 is positively correlated with the tumor cell apoptosis index in cell carcinoma." (PMID 34335934, 2021). "We then investigated the relationships between the eight E2Fs and tumor immunology and found that E2F1, E2F3, E2F5, E2F6, and E2F7 expression was positively correlated with many immune cells, which might explain their favorable prognostic value." (PMID 34617871, 2021). "Therefore, E2F1 can act both as an oncogene and as a tumour suppressor, depending upon the cellular context (Engelmann and Pützer 2012)." (PMID 33691613, 2021). "Taken together, downregulation of HNF4α may lead to the upregulation of lnc‐APUE, and lnc‐APUE may work as a miR‐20b sponge to prevent the miR‐20b‐mediated repression on E2F1 expression, thereby promoting G1/S transition and tumor growth." (PMID 33854885, 2021). "Other previous studies have found, using transcriptional analysis, that the GSK3β-E2F1 axis may be involved in neuronal apoptosis and differentiation, as well as tumor growth, and has several direct effects on its downstream effectors." (PMID 34572310, 2021). "Abnormal activation of E2F1 has been studied in various tumor types in recent years." (PMID 34079762, 2021). "Furthermore, E2F1 was found to play a vital role in the regulation of tumour cell proliferation, invasion, and metastasis in KIRC." (PMID 34531911, 2021).
tumor (continued). "Overexpression of E2F1 is reported in HCC tumors as compared with non-tumor tissues." (PMID 33777103, 2021). "Stably transfected RT4 cells were subcutaneously inoculated into nude mice to explore whether TMPO-AS1 would promote BC growth via E2F1 in vivo; every 5 days, the tumor volumes were measured." (PMID 33816295, 2021). "Taken together, the key findings of the current study provide evidence demonstrating the promoting mechanism of LINC00319 on cell proliferation, invasion, and self-renewal ability in vitro and tumor growth in vivo in LSCC by increasing HMGB3 expression via recruitment of E2F1." (PMID 34408262, 2021). "Therefore, it is evident from these results that E2F1 plays an important role in skewing the cancer spliceome to meet the altered adaptive requirement in the hypoxic tumor niches." (PMID 34362878, 2021). "Paradoxically, E2F1 can also inhibit tumor growth by inducing cell senescence and apoptosis." (PMID 34499617, 2021). "Moreover, in addition to exerting cell cycle control, E2F1 regulates the expression of a class of genes critical for angiogenesis, interactions between tumor cells and mesenchymal cells and ECM remodeling to promote invasion and metastasis." (PMID 34350181, 2021). "In addition, overexpression of E2F1 suppressed tumor growth and promoted tumor cell apoptosis in nude mice implanted with E2F1-overexpressing MGC-803 cells." (PMID 34136392, 2021). "Previous studies using Neu and PyMT models predicted a key role for the E2F1 transcription factor through a pathway signature analysis, suggesting that mechanisms outside the overexpression of the Neu or PyMT oncogene were contributing to tumor biology." (PMID 33947907, 2021). "Moreover, the inhibitory effect of USP2-AS1 knockdown on in vivo xenograft tumor growth was greatly reversed by E2F1 induction." (PMID 34707111, 2021). "However investigation of these models through whole genome sequencing found numerous differences between the models, including differences in the proposed tumor etiology between E2F1−/− and E2F1+/+ tumors induced by Neu or PyMT." (PMID 33947907, 2021). "In GC, upregulated E2F1 expression, targeting the TINCR/STAU1/CDKN2B signaling axis, was positively associated with poor prognosis due to its association with advanced stage and larger tumor size." (PMID 34532281, 2021). "PRR11 may have been a potential target for the treatment of ccRCC in the clinic treatment and may have promoted tumor development by affecting the stability of E2F1." (PMID 34499617, 2021). "Research suggests that E2F1 plays a vital role in tumor invasion, proliferation, and migration." (PMID 34521301, 2021). "E2F-1 regulates parts of the Rb-p16 pathway which is defective in many tumor cells." (PMID 35004328, 2021). "Its tumor suppressive function is due to inhibition of the transcription factor E2F1." (PMID 33407425, 2021). "LncRNA-HAGLR represses tumor growth of NSCLC by epigenetically inhibiting E2F1." (PMID 33589572, 2021).
tumor (continued). "In conclusion, our study highlighted RFWD3 may function as a tumor promotor in CRC via E2F1 transcriptional regulation of BIRC5, which might be used as a future therapeutic target for the more effective treatment of CRC." (PMID 34712656, 2021). "E2F1 expression induced VMP1 mRNA expression in PANC-1 tumor cells." (PMID 32655498, 2020). "Furthermore, safranal-treated tumor tissues exhibited a reduction in Skp2, E2F1, NF-κB p65, p-IκBα (Ser32), c-MYC, p-Rb (Ser807), CDK4, CDK6, and CDK2 and an elevation of p27 and p21 protein levels." (PMID 33392189, 2020). "E2F1 is a transcription factor with activities related to either inhibiting or stimulating the development of the tumours; therefore, it could be considered a modulator of cell growth and death." (PMID 32316225, 2020). "Our study suggests that in PitNETs, E2F1 could be a good biomarker of invasiveness, and miR-17-5p of proliferation, helping the clinical management of these tumours." (PMID 32316225, 2020). "But the expression of E2F1 in PAAD patients has nothing to do with the tumor stage." (PMID 33604289, 2020). "In addition, the same integrin, as observed for E2F1, appears to exert an oncogenic or tumor suppressor function depending on the genetic background of the different cancer cells." (PMID 32813746, 2020). "Previous studies have elucidated that CDK6 could phosphorylate Rb protein, induces the expression of E2F1, thus inducing the transformation from G1 to S phase, promoting cell proliferation and acting as a tumor promotor in human cancer." (PMID 32310823, 2020). "Potentially, targeting CDK8 for inhibition, at least in CDK8 over-expressing tumors, could help restore e2f1 activity in these tumors, promoting inhibition or regression of tumor growth." (PMID 32596239, 2020). "Furthermore, owing to this, ablation of Parp1 transcriptional activity was shown to counteract the effects of E2f1-induced hyper-replication on embryonic development and tumour growth." (PMID 33050515, 2020). "In this study, we proved the tumour‐activator role of p300 in an E2F1‐dependent mechanism." (PMID 32951317, 2020). "Moreover, downregulation of miR-362-5p promoted the protein levels of QKI, MacroH2A1.1, PARP-1, p27 in tumor tissues, while reduced the protein levels of Cyclin D, MacroH2A1.2, c-Fos, and E2F1." (PMID 32194406, 2020). "E2F1, a member of the E2F family of transcription factors, has been reported to play a crucial role in the control of the cell cycle, as well as induce tumor cell EMT." (PMID 32668414, 2020). "Indeed, in the present study, we observed higher expression of E2F1 in invasive versus non-invasive tumours in the whole series and in the ST subtype." (PMID 32316225, 2020). "Therefore, inhibition of E2F1 suppresses the re-activation of QCCs and the further advancement of cells to the S phase, exerting multiple inhibitory effects on tumor recurrence and progression." (PMID 33392189, 2020). "However, the tumor volumes of the cisplatin with Si-E2F1 group were higher than those of the cisplatin group." (PMID 31897226, 2020). "Furthermore, the expression of IGF2BP1, METTL3 and METTL14 is strongly correlated with E2F1–3 expression (R = 0.4) across 33 TCGA tumor cohorts." (PMID 32761127, 2020). "Moreover, studies have also reported that oxidative stress, which is an important aspect of tumor microenvironment, downregulates miR-20b-5p and E2F1 via overexpression of HMGA2." (PMID 32752229, 2020). "A protein that helps repair damaged DNA, E2F1, paradoxically also promotes tumor growth." (PMID 31534120, 2019).
tumor (continued). "This study expands on this finding and adds to the growing body of research that has demonstrated E2F1 as a key regulator of angiogenesis; suggesting E2F1 regulates many genes within the hypoxia response program to potentially coordinate the development of tumor vasculature." (PMID 31341204, 2019). "Replacement of the endogenous promoter of adenovirus type 5 with the E2F-1 promoter may construct the recombinant adenovirus highly expressed E2F-1 gene in tumor tissues." (PMID 31278126, 2019). "Furthermore, SG400-E2F/IL-15 injection triggered cell rupture in E2F1-positive tumor cells as well as a large amount of tissue necrosis." (PMID 31278126, 2019). "In addition, MZF1‐AS1 binds poly(ADP‐ribose) polymerase 1 (PARP1) to facilitate its interaction with E2F transcription factor 1 (E2F1), resulting in transactivation of E2F1 and upregulation of MZF1 and other oncogenic genes associated with tumor progression." (PMID 31592410, 2019). "In sporadic BL tumour samples, as well as in BL cell lines, E2F1 expression is deregulated." (PMID 31683676, 2019). "Moreover, the growth of an ACTH-secreting tumor cell line was deeply reduced by the E2F1 inhibitor HLM 006474." (PMID 31487906, 2019). "We examined whether the E2F1-induced tumor cell motility is clinically relevant through Kaplan-Meier analysis." (PMID 30813560, 2019). "The tumor-suppressive effect of E2F1 has been ascribed to occur at the cancer promotion stage and may involve the induction of autophagy and apoptosis." (PMID 31616639, 2019). "Blocking E2F1 expression by RNA interference might represent a promising therapeutic approach in this type of tumours." (PMID 29661169, 2018). "E2F8 was found to be markedly overexpressed in HCC to facilitate tumor occurrence and development via activation of an E2F1/cyclin D1 signaling pathway to regulate the G1- to S-phase transition of cell cycle progression or transcriptionally suppress CDK1 to induce hepatocyte polyploidization." (PMID 30326936, 2018). "However, previous studies indicated that E2F1 played a tumour suppressing role in GC, and this was due to apoptosis being induced by adenovirus-mediated overexpression of E2F1." (PMID 30487158, 2018). "Furthermore, deguelin inhibits tumor cell propagation and malignant transformation through p27-cyclinE-pRb-E2F1 cell cycle control and HIF-1α-VEGF anti-angiogenic pathways." (PMID 29416603, 2018). "In human specimens, the downregulation of HMGA1, E2F1, and vimentin, analyzed by IHC, compared with the basal levels found in the biopsies revealed that trabectedin therapy reduces the mesenchymal markers of the tumor." (PMID 29980789, 2018). "UHRF1 overexpression relates to metastasis, tumor stage, E2F1 levels and poor survival rate." (PMID 28881702, 2017). "Moreover, the SNP in rs35301225 of miR-34a was associated with tumor size and tumor differentiation, as well as metastasis in CRC patients; C/A SNP was related to the significantly enhanced expression of E2F1 and shorter survival in post-surgery CRC patients." (PMID 28293146, 2017). "E2F1 is a transcription factor that takes part in regulating various biological activities, including the cell cycle, apoptosis, proliferation, angiogenesis, tumour drug resistance, invasion and metastasis and so on." (PMID 29115924, 2017). "E2F1 (E2F transcription factor 1) can act as a tumor suppressor or oncogene." (PMID 28146423, 2017). "Additionally, it has been shown that E2F1-mediated repression of oxidative metabolism results in a self-renewal of tumor-initiating stem-like cells that contributes to the progression of HCC." (PMID 29176962, 2017). "E2F1 overexpression promoted tumor growth in vivo; miR-519d overexpression inhibited it." (PMID 28146423, 2017). "This may be due to p21 inhibiting cellular growth by pathways not regulating cell cycle, for instance, during notch 1 activation, p21 suppressed E2F1-dependent Wnt4 expression to inhibit tumor cell proliferation." (PMID 28522974, 2017).
tumor (continued). "Moreover, patients with higher E2F1 levels appeared to have a greater tumor size, higher tumor stage and shorter survival than the lower group." (PMID 28569791, 2017). "Given that a mutation at a miRNA target site may impair gene expression, we evaluated E2F1 gene expression by comparing tumor and normal adjacent tissues." (PMID 28704519, 2017). "We report the first evidence that the SNP rs35301225 located in miR-34a might be a protective factor to prevent the binding on 3′UTR of E2F1, which might suppress tumor growth in human CRC." (PMID 28293146, 2017). "Our findings suggest that IAP-targeting molecules could be tested for their ability to overcome E2F1 activity in tumor cells, for example, in an Rb-compromised setting." (PMID 28542143, 2017). "Furthermore, the up-regulated genes contain fewer tumor-related transcription factors such as cMyc/nMyc and E2f1, indicating that demethylation by miRNA and shRNA is better for the quality of iPSCs." (PMID 28155862, 2017). "E2F1 plays a critical role in the control of cell cycle and acts as a tumor suppressor." (PMID 28359318, 2017). "Another TF, E2F1, promoted the apoptosis and acted as tumor suppressor." (PMID 29069717, 2017). "One of the potential mechanisms that underline the DNMT3B-mediated arrest involves the ability of DNMT3B siRNA to reduce the expression of different cyclins (Cyclin B1, Cyclin D1 and Cyclin E2) and to block the pRB/E2F1 pathway by inducing de-phosphorylation of RB tumour suppressor." (PMID 27764816, 2016). "Cdc6 and immunoprecipitated E2F1 were also positively correlated with tumor mass." (PMID 27077880, 2016). "However, some TS+ tumors were E2F1+ and others were E2F1- indicating different mechanisms used by tumor cells to increase TS level and acquire resistance to treatment." (PMID 26831819, 2016). "E2F1 also regulated apoptosis, senescence, and autophagy under specific conditions, including DNA damage or repair, which are correlated with tumor progression." (PMID 27175585, 2016). "E2F1 maintains a balance between tumor proliferative and tumor suppressive functions." (PMID 27806706, 2016). "However, E2F1 plays an accelerative role in cell cycle regulation of tumor growth, which is dependent on pRB and CDKs." (PMID 27708221, 2016). "Because the promoter methylation of E2F1-dependent proapoptotic genes is a step in apoptotic defense mechanisms, the simultaneous inhibition of both SET9 and DNMT1 in the presence of DNA damage may be required to favor the tumor-suppressor function of E2F1." (PMID 27054335, 2016). "Although E2F1 induces apoptosis and decreased proliferation in cell lines and tumor tissue in CRCs, there is evidence that high E2F1 expression may be associated with CRC progression and metastasis." (PMID 26831819, 2016). "It has been reported that E2F1 plays an important role in tumor angiogenesis." (PMID 26540633, 2016). "However, the PUF60, BOP1, and E2F1 genes were found to be significantly over-expressed in tumor tissues with copy number gains." (PMID 26360582, 2015). "Here, we addressed that the tumour suppressing miR-34c was probably another bona fide target of E2F1 and could be positively regulated by E2F1." (PMID 26704889, 2015). "The human E2F1 promoter is active in most tumor cell lines mutated in the pRb pathway thus facilitating the use of the E2F1 promoter in most if not all tumors." (PMID 25714011, 2015). "Moreover, cyclins D & E, E2F1 and CDK4 and 6, have all been previously observed to be associated with poor outcome in a number of other tumour types." (PMID 25738365, 2015). "However, E2F1 also induces an apoptotic gene expression program, which has been postulated to suppress tumor initiation by eliminating cells that have acquired a single oncogenic mutation in the RB pathway." (PMID 25907958, 2015). "We examined the effect of gain of POH1 function on E2F1 activity in tumour cells." (PMID 26510456, 2015). "Knockout of E2F1 or E2F3 significantly delayed tumor onsets." (PMID 26512919, 2015).